MIR1178 (microRNA 1178)
Synonyms: hsa-mir-1178; MIRN1178
Gene: MicroRNA gene on chromosome 12 (119,713,634 to 119,713,724, reverse strand). Ensembl gene ENSG00000283768.
Gene Ontology:
Biological process: miRNA-mediated post-transcriptional gene silencing
Cellular component: RISC complex